EIF4E (eukaryotic translation initiation factor 4E)
Diseases named in the same sentence as EIF4E in open-access papers (continued):
Sharing a sentence is not in itself a finding about the gene and the disease.
Hyperkeratosis (1 paper, 2022). Hyperkeratosis is a histopathological term defining a thickened stratum corneum and may be present in many different skin conditions, with many possible overlaps. "Patients with hyperkeratosis and parakeratosis, acanthosis thickening had increased expression of 13 the same genes, including SQLE, STRN, EIF4E, and MYO1B." (PMID 35277199, 2022). "Therefore, we speculate that AP-1 upregulates the expression of SQLE, STRN, EIF4E, and MYO1B; it brings keratinocytes EMT, which further mediates hyperkeratosis with parakeratosis and acanthosis thickening." (PMID 35277199, 2022).
hypopharyngeal cancer (1 paper, 2023). Carcinoma, predominantly squamous cell, arising from the epithelial cells of the hypopharynx. "In hypopharyngeal cancer specimens, the elevated expression of eukaryotic translation initiation factor 4E (eIF4E), a downstream mTOR effector, is associated with increased lymphatic density within metastatic lymph nodes." (PMID 38201272, 2023).
iron deficiency (1 paper, 2024). "To determine whether mTOR modulates bulk translation during iron deficiency, we determined the phosphorylation state of the eIF4E-binding protein (4EBP1), which decreases under stress conditions due to a drop in mTOR activity, resulting in recruitment of eIF4E and translation impairment." (PMID 38605136, 2024).
keratitis (1 paper, 2021). A corneal disease that is characterized by inflammation of the cornea. "In vitro investigations showed that 4E1RCat also halted the decrease in interleukin-1β production, myeloperoxidase levels, and neutrophil recruitment in murine Aspergillus fumigatus keratitis by means of inhibiting eIF4E/4E-BP1 binding, as well as stopping the increase in fungal load and apoptosis." (PMID 33802476, 2021).
laryngeal squamous cell carcinoma (1 paper, 2023). A squamous cell carcinoma that arises from the larynx. "EIF4E and bFGF played a synergistic role in the genesis, development, invasion and metastasis of laryngeal squamous cell carcinoma." (PMID 37601696, 2023).
malignant mesothelioma (1 paper, 2015). A malignant neoplasm of the pleura or peritoneum, arising from mesothelial cells. "In conclusion, we suggest that modulation of eIF6 levels and activity may lead to a therapeutical avenue in tumor therapy, especially where eIF4E inhibition by rapalogs is not effective, as in malignant mesothelioma." (PMID 26462016, 2015).
metastasis (1 paper, 2024). The spread or migration of cancer cells from one part of the body (where they first appeared) to another. "Studies show when it is overexpressed it results in more frequent liver metastasis, suggesting the prognostic effect of EIF4E on colorectal liver metastasis." (PMID 38051091, 2024).
metastatic cancer (1 paper, 2014). A carcinoma which has spread from the original site of growth to another anatomic site. "The positive percentage of p-eIF4E expression in the primary NPC tissue was significantly lower than that in the matched metastatic cancer (p = 0.016)." (PMID 24551240, 2014).
microcephaly (1 paper, 2020). A congenital or acquired developmental disorder in which the circumference of the head is smaller than normal for the person's age and sex. "In mice, loss of a single copy of Rbm8a or other EJC genes (Magoh or Eif4e) causes microcephaly and severe neural defects." (PMID 32773035, 2020).
muscle atrophy (1 paper, 2026). The loss of muscle tissue due to inactivity or disease. "This is supported by the downregulation of the E3 ubiquitin ligases MAFbx and MuRF1, hallmarks of skeletal muscle atrophy, and activation of key nodes in protein synthesis, S6K1 and eIF4E." (PMID 41541654, 2026).
myeloid leukemia (1 paper, 2023). A clonal proliferation of myeloid cells and their precursors in the bone marrow, peripheral blood, and spleen. "PRH is up-regulated in certain types of lymphoid leukemia, while it is down-regulated and eIF4E is up-regulated in some types of myeloid leukemia (AML, CML)." (PMID 37601696, 2023).
myxoid liposarcoma (1 paper, 2016). A liposarcoma characterized by the presence of round non-lipogenic primitive mesenchymal cells and small signet ring lipoblasts within a myxoid stoma with a branching vascular pattern. "To examine a potential association between FUS-CHOP and eIF4E expression and the angiogenic activity of myxoid liposarcoma cells, we examined the effect of siRNA knockdown on the expression and activity of proangiogenic factors." (PMID 27822137, 2016). "Our findings demonstrate that eIF4E expression is critical for myxoid liposarcoma cell survival and proliferation." (PMID 27822137, 2016). "Both chemical inhibition and siRNA knockdown of eIF4E markedly reduced the viability of two myxoid liposarcoma cell lines, demonstrating that the expression and activity of eIF4E are required for myxoid liposarcoma cell growth." (PMID 27822137, 2016). "The success of the eIF4E inhibitor 4EGI-1 in our initial screen pointed to a role for this oncoprotein in myxoid liposarcoma." (PMID 27822137, 2016). "Similar to our finding that FUS-CHOP promotes angiogenesis, we also demonstrated that eIF4E promotes the production of angiogenic factors in myxoid liposarcoma cell lines, as eIF4E siRNA knockdown significantly reduced the expression of VEGFA, VEGFB, and VEGFR3." (PMID 27822137, 2016). "This is supported by a previous report showing that eIF4E is overexpressed in myxoid liposarcoma and may by critical to tumor development." (PMID 27822137, 2016). "To investigate the importance of FUS-CHOP and eIF4E expression in myxoid liposarcoma, we performed siRNA knockdown of CHOP (using a CHOP-directed siRNA, which also targets FUS-CHOP) or eIF4E in the myxoid liposarcoma cell lines." (PMID 27822137, 2016). "Thus, both eIF4E and FUS-CHOP contribute to the angiogenesis observed in myxoid liposarcoma cells through the regulation of angiogenic receptors and ligands." (PMID 27822137, 2016). "Similarly, pharmacologic inhibition of eIF4E by 4EGI-1 decreased the expression of VEGFR1, VEGFR3, VEGFA, and VEGFB in myxoid liposarcoma cell lines." (PMID 27822137, 2016). "Therefore, both eIF4E and FUS-CHOP are critical to myxoid liposarcoma cell proliferation and survival." (PMID 27822137, 2016).
parasitemia (1 paper, 2020). "Importantly, we demonstrate that genetic ablation of eIF4E phosphorylation dramatically increases parasite replication in vitro as well as parasitemia and host susceptibility in an experimental toxoplasmosis model." (PMID 33014898, 2020). "Functions of eIF4E beyond translation initiation per se are yet to be investigated in the context of parasitic infections." (PMID 33014898, 2020). "The increased replication rate in vitro, and parasitemia and virulence in eIF4E S209A KI mice suggest that preventing eIF4E phosphorylation favors T. gondii persistence within its host." (PMID 33014898, 2020). "Similarly, parasitemia in the mesenteric lymph nodes and spleen, as well as brain cyst burden were significantly augmented in infected eIF4E S209A knock-in mice compared to their WT counterparts." (PMID 33014898, 2020).
psoriasis (1 paper, 2022). An autoimmune condition characterized by red, well-delineated plaques with silvery scales that are usually on the extensor surfaces and scalp. "Here we provide results that an increased expression of EIF4E in psoriasis is consistent with a previous experiment." (PMID 35277199, 2022). "In this regard, it is interesting to note that AP-1 upregulates the gene expression of SQLE, STRN, EIF4E, and MYO1B might to promote the abnormality of keratinocytes and immune system to mediate the occurrence of psoriasis." (PMID 35277199, 2022).
renal carcinoma (1 paper, 2025). A carcinoma arising from the epithelium of the renal parenchyma or the renal pelvis. "Research has shown that eIF4E mediates enhanced translation of proto-oncogenes, promotes proliferation and invasion of renal cancer, and is closely associated with sunitinib resistance." (PMID 40809690, 2025). "Disturbed expression of eIF4E in renal cancer may be associated with poor prognosis." (PMID 40809690, 2025).
Renal cyst (1 paper, 2021). A fluid filled sac in the kidney. "While OFD1 weakly binds mRNA, the presence of BICC1, an RNA-binding protein also found at the centrosome, allows OFD1 to mediate a stronger association between eIF4F via eIF4E and several centrosomal mRNAs that are implicated in ciliogenesis and renal cyst formation." (PMID 34805187, 2021).
Rotavirus infection (1 paper, 2019). Infection with any of the rotaviruses. "Similarly, a lentiviral RNAi-mediated loss-of-function assay was performed to silence the eIF4E gene to assess its effect on rotavirus infection." (PMID 30934842, 2019). "The effect of eIF4A, eIF4E, and eIF4G on rotavirus infection was further detected by RT-qPCR and western blot, demonstrating that both viral genomic RNA and viral protein VP4 synthesis were promoted." (PMID 30934842, 2019). "We first examined the effects of rotavirus infection on the expression of the components of the eIF4F complex, including eIF4A and eIF4E, at indicated time points (1, 2, 4, 6, 24, and 48 h)." (PMID 30934842, 2019).
Sensory neuropathy (1 paper, 2019). Peripheral neuropathy affecting the sensory nerves. "This is the first demonstration that sensory neuropathy affects cardiac miRNA expression network targeting IGF-1, SLC2a-12, EIF-4e, and ULK-2, which may contribute to cardiac diastolic dysfunction induced by sensory neuropathy." (PMID 30823517, 2019). "This is the first demonstration that sensory neuropathy induced by capsaicin desensitization affects cardiac miRNA expression network targeting IGF-1, SLC2a-12, EIF-4e, and ULK-2, which may contribute to cardiac diastolic dysfunction induced by sensory neuropathy." (PMID 30823517, 2019).
squamous cell carcinoma (1 paper, 2012). A carcinoma arising from squamous epithelial cells. "Ribavirin also inhibited eIF4E-associated transformation of cells in vitro and eIF4E-dependent squamous cell carcinoma of human in in vivo mouse model." (PMID 23164412, 2012).
T-cell lymphoma (1 paper, 2019). "Similarly, it has been reported that U0126 cannot inhibit eIF4E phosphorylation in T-cell lymphoma and hepatocellular carcinoma." (PMID 30804329, 2019).
thyroid cancer (1 paper, 2021). "The expression of eIF4E in thyroid carcinoma (THCA), kidney renal papillary cell carcinoma (KIRP), and kidney renal clear cell carcinoma (KIRC) was significantly lower than that in the normal control samples." (PMID 34876062, 2021).
toxoplasmosis (1 paper, 2020). A parasitic disease contracted by the ingestion or fetal transmission of toxoplasma gondii. "To further extent our in vitro observations and to determine the impact of eIF4E phosphorylation on the outcome of toxoplasmosis, we infected and compared WT and eIF4E S209A KI mice." (PMID 33014898, 2020). "In summary, the absence of eIF4E phosphorylation appears to compromise host resistance against toxoplasmosis despite increased IFNγ production." (PMID 33014898, 2020). "Also, it is conceivable that complete absence of eIF4E phosphorylation in infected but also in uninfected 4E KI cells and mice precludes an appropriate immune response to develop against toxoplasmosis." (PMID 33014898, 2020).
urothelial carcinoma (1 paper, 2021). A malignant neoplasm derived from the transitional epithelium of the urinary tract (urinary bladder, ureter, urethra, or renal pelvis). "Urothelial carcinoma is associated with increased protein synthesis and phosphorylation of the translation initiation factor eIF4E." (PMID 34032633, 2021). "This study and the prevalence of eIF4E hyperphosphorylation within muscle-invasive bladder cancer provide the preclinical rationale for conducting phase 2 studies in urothelial carcinoma patients." (PMID 34032633, 2021). "To determine the number of muscle invasive bladder cancer patients who could potentially benefit from an inhibitor of eIF4E phosphorylation, we conducted phospho-eIF4E S209 IHC of human urothelial carcinoma tissue specimens." (PMID 34032633, 2021).
cancer (400 papers, 2002 to 2026). A tumor composed of atypical neoplastic, often pleomorphic cells that invade other tissues. "In some cases, especially in the progression of certain cancers, abnormal activation of this axis causes excessive eIF4E phosphorylation, thereby promoting growth, proliferation and cancer cell metastasis." (PMID 37864471, 2023). "eIF4E has been shown to regulate gene subsets related to key stress reactions, a function that is critical to cancer induction and progression and is usually linked to a substantial increase in eIF4E level to protect cells against ROS accumulation." (PMID 36225177, 2022). "Human and experimental cancers have been associated with high levels of eIF4E expression with links to angiogenesis and tumor growth." (PMID 36555391, 2022). "Several sources have reported that overexpression of MNKs and p-eIF4E were associated with the progression and development of cancer." (PMID 35877722, 2022). "To date, the oncogenic roles of MNK1/2 and phosphorylated eIF4E have been implicated in various cancers." (PMID 33564073, 2021). "eIF4E is a limiting factor in translation initiation and its overexpression is a hallmark in many cancers." (PMID 35582305, 2021). "An increase in phosphorylated 4EBP1 and/or eIF4E is linked to poor prognosis in a variety of cancers including head and neck cancer." (PMID 35048066, 2021). "It is clearly established that dysregulation in the activity of eIF4E can be the primary cause of different types of diseases, such as cancer and neurodevelopmental disorders." (PMID 34541613, 2021). "This function is particularly important in cancer and tumor development, which is often associated with a major increase in eIF4E levels to protect the cells from ROS accumulation." (PMID 31906869, 2020). "CRM1 also plays an important role in the Eukaryotic translation initiation factor 4E (eIF4E) dependent export of mRNAs, which encode proteins involved in cell proliferation and survival, as well as the formation of cancer metastasis." (PMID 32932882, 2020). "eIF4E is a 5′ cap-dependent translation initiation factor that is reportedly overexpressed in multiple cancers, where it is associated with aggressive phenotypes." (PMID 32967226, 2020). "High eIF4E and low p-eIF4E expression was marginally associated with cancer-specific survival (CSS) (p = 0.105 and 0.114, respectively) but not with OS." (PMID 31258849, 2019). "eIF4E is persistently hyperactivated due to genetic alterations of pathway components located upstream of the 4EBP1/eIF4E axis, as the genes encoding 4EBP1 and eIF4E remain normal in the vast majority of cancers, including RCC." (PMID 31258849, 2019). "The relative limitation of eIF4E levels in the cell renders it an important factor for translation control, and its aberrant expression is associated with cancer development." (PMID 31671902, 2019). "Another important driver of cap-dependent translation, eIF4E has been associated with the aggressiveness of cancer." (PMID 29748619, 2018). "As a consequence, overexpression and hyperactivation of eIF-4E cause malignant transformation and metastasis in various cancers." (PMID 28054974, 2017). "eIF4E overexpression alone leads to oncogenic transformation in mouse models and its elevation in cancer is linked to poor prognosis." (PMID 28325843, 2017). "This constitutively active mTORC1 causes eIF4E-driven translation to be hyperactive in most cancers and is currently a major target of cancer therapeutics." (PMID 29317983, 2017). "Expression of eIF4E is commonly elevated in human and experimental cancers and has been associated with promoting angiogenesis and tumor growth." (PMID 28978144, 2017). "eIF4E overexpression/activation correlates with poor clinical outcome in human cancers as it promotes the translation of carcinogenesis associated mRNAs." (PMID 27926520, 2017).
cancer (continued). "Constitutively active mTORC1 causes eIF4E-driven translation to be hyperactive in most cancers and is currently a major target of cancer therapeutics." (PMID 29317983, 2017). "Its overexpression is linked to tumorigenesis in various human cancers, suggesting that the levels of eIF4E must be under tight control in normal cells." (PMID 28852129, 2017). "Around 30% numbers of cancers exhibit elevated eIF4E expression, which is associated with poor prognosis." (PMID 26942880, 2016). "A plenty of distinct mechanisms including PI3K amplification/mutation, PTEN loss of function, Akt overexpression, and S6K1 or eIF4E overexpression can result in the constitutive activation of the PI3K/Akt/mTOR pathway in cancer cells." (PMID 26940018, 2016). "Silencing of eIF4E slows down proliferation, and causes arrest of the cell cycle in the G0/G1 phase, as well as increased apoptosis in many cancer types." (PMID 26672765, 2016). "eIF4E has a key regulatory role in initiating mRNA translation, which is known to be up-regulated in a variety of human cancers and is linked to poor prognosis." (PMID 27050281, 2016). "Dysregulated mRNA translation in cancer cells is often associated with high levels of eIF4E, and eIF4E overexpression is sufficient to drive lymphomagenesis." (PMID 27579538, 2016). "Phosphorylation of the eukaryotic translation initiation factor eIF4E is associated with malignant progression and poor cancer prognosis." (PMID 25923732, 2015). "Use of rapamycin as a therapeutic agent in the development of cancer has been studied since this drug specifically inhibits mTOR kinase by causing 4EBP hypophosphorylation, resulting in eIF4E hijacking." (PMID 25690796, 2015). "eIF4E has been associated with cancer development and progression, and proposed as an important therapeutic target." (PMID 26041884, 2015). "The sensitivity to rapalogs has been associated to low eIF4E/4EBP1 ratios, whereas increased eIF4E expression and/or decreased 4EBP1 expression confer resistance in cancer cells." (PMID 25026292, 2014). "eIF4E overexpression is common in multiple cancer types and clearly linked with poor clinical outcome and decreased patient survival." (PMID 24260583, 2013). "mTOR downstream effectors S6K1, 4EBP1 and eIF4E are implicated in cellular transformation, and their overexpression has been linked to poor cancer prognosis." (PMID 22408430, 2012). "Overexpression of eIF4E is sufficient to induce transformation of fibroblasts and primary epithelial cells in culture, and eIF4E overexpression in mice leads to increased cancer susceptibility in a range of tissues." (PMID 21772331, 2011). "eIF4E itself has been recognized as an oncoprotein implicated in tumor cell proliferation and tumor progression in multiple cancer sites including breast and lung." (PMID 19290046, 2009). "Given that elevated eIF4E levels are found in many human cancers and are associated with poor prognosis, it is critical to understand how eIF4E levels become elevated." (PMID 20049173, 2009). "There is a wealth of literature on eIF4E expression in cancer and, although patient cohorts used have been relatively small (<200 individuals), the conclusion that high eIF4E levels are associated with poor prognosis is well established." (PMID 19367274, 2009). "The importance of eIF4E in cancer has been underlined by the fact that eIF4E expression levels can be used to determine prognosis." (PMID 19367274, 2009). "Cancer specimens exhibiting high levels of eIF4E expression increase the patient's relative risk for cancer recurrence as compared to patient cancer specimens with low eIF4E expression." (PMID 17010208, 2006). "A recent study introduced MDA‐MB‐435 cell lines expressing different eIF4E variants, which provided insights into how variations in eIF4E function could influence cancer cell behavior." (PMID 41208200, 2025).